SKP2 (S-phase kinase associated protein 2)
Description:
Substrate recognition component of a SCF (SKP1-CUL1-F-box protein) E3 ubiquitin-protein ligase complex which mediates the ubiquitination and subsequent proteasomal degradation of target proteins involved in cell cycle progression, signal transduction and transcription. Specifically recognizes phosphorylated CDKN1B/p27kip and is involved in regulation of G1/S transition (By similarity). Degradation of CDKN1B/p27kip also requires CKS1 (By similarity). Recognizes target proteins ORC1, CDT1, RBL2, KMT2A/MLL1, CDK9, RAG2, NBN, FOXO1, UBP43, YTHDF2, and probably MYC, TOB1 and TAL1. Degradation of TAL1 also requires STUB1. Recognizes CDKN1A in association with CCNE1 or CCNE2 and CDK2. Promotes ubiquitination and destruction of CDH1 in a CK1-dependent manner, thereby regulating cell migration. Following phosphorylation in response to DNA damage, mediates 'Lys-63'-linked ubiquitination of NBN, promoting ATM recruitment to DNA damage sites and DNA repair via homologous recombination. Through the ubiquitin-mediated proteasomal degradation of hepatitis C virus non-structural protein 5A, has an antiviral activity towards that virus.
Synonyms: FBXL1; FBL1; p45; FLB1
Tractability: Small molecule: a structure with a bound ligand is known; a high-quality ligand is known; it has a binding pocket of medium quality. PROTAC: UniProt records ubiquitination sites on it; ubiquitination databases record sites on it; a small molecule that binds it is known.
Gene: Protein-coding gene on chromosome 5 (36,151,989 to 36,196,849, forward strand). Ensembl gene ENSG00000145604.
Subcellular location: Cytoplasm; Nucleus
Subcellular location (Human Protein Atlas): Cytosol; Nucleoplasm; Nucleoli
Pathways (Reactome):
Cell Cycle: APC/C:Cdh1 mediated degradation of Cdc20 and other APC/C:Cdh1 targeted proteins in late mitosis/early G1; Cyclin D associated events in G1; SCF(Skp2)-mediated degradation of p27/p21
Metabolism of proteins: Neddylation; Ub-specific processing proteases
Cellular responses to stimuli: Regulation of BACH1 activity
DNA Replication: Orc1 removal from chromatin
Disease: Aberrant regulation of mitotic exit in cancer due to RB1 defects
Gene expression (Transcription): Regulation of RUNX2 expression and activity
Immune System: Antigen processing: Ubiquitination & Proteasome degradation
Gene Ontology:
Molecular function: identical protein binding; protein binding; ubiquitin-like ligase-substrate adaptor activity
Biological process: defense response to virus; innate immune response; positive regulation of double-strand break repair via homologous recombination; proteasome-mediated ubiquitin-dependent protein catabolic process; protein K48-linked ubiquitination; protein K63-linked ubiquitination; regulation of apoptotic process; G1/S transition of mitotic cell cycle; SCF-dependent proteasomal ubiquitin-dependent protein catabolic process; protein ubiquitination; ubiquitin-dependent protein catabolic process
Cellular component: cytoplasm; cytosol; nucleolus; nucleoplasm; nucleus; SCF ubiquitin ligase complex
Genetic constraint (gnomAD): Loss-of-function variants: 11 observed, 34.07 expected, observed/expected ratio (o/e) 0.32, 90% interval 0.2 to 0.53. The upper end of that interval is the gene's LOEUF score, 0.53, which puts it in group 2 of 6, group 1 being the genes least tolerant of losing a copy. Missense variants: 289 observed, 399.3 expected, observed/expected ratio (o/e) 0.72, 90% interval 0.66 to 0.8. Synonymous variants: 139 observed, 164.76 expected, observed/expected ratio (o/e) 0.84, 90% interval 0.73 to 0.97.
Homologues: Orthologues: chimpanzee SKP2 (99% identical), macaque SKP2 (98% identical), pig SKP2 (94% identical), guinea pig Skp2 (91% identical), rat Skp2 (87% identical), mouse Skp2 (86% identical), dog SKP2 (83% identical), tropical clawed frog skp2 (57% identical), zebrafish skp2 (45% identical), Drosophila melanogaster Skp2 (27% identical), Drosophila melanogaster CG9003 (20% identical), Caenorhabditis elegans skpt-1 (20% identical), and 23 more. Paralogues in human: FBXL13 (21% identical), FBXL7 (21% identical), FBXL2 (19% identical), FBXL20 (19% identical), FBXL18 (18% identical), FBXL19 (18% identical), FBXL4 (18% identical), FBXL5 (18% identical), FBXL6 (17% identical), FBXL14 (15% identical), FBXL16 (15% identical), FBXL17 (14% identical), and 3 more.
Diseases named in the same sentence as SKP2 in open-access papers:
SKP2 is named in the same sentence as 199 diseases in open-access papers, as found by Europe PMC text mining. Sharing a sentence is not in itself a finding about the gene and the disease. The quoted sentences say what the papers report.
breast carcinoma (144 papers, 2005 to 2026). "Programmed Death-Ligand 1 (PD-L1) promotes tumor progression through several mechanisms, including its intrinsic effect on breast cancer cell proliferation via the S-Phase Kinase-Associated Protein 2 (SKP2)-p21Cip1/p27Kip1 (SKP2-p21/p27) axis." (PMID 41898602, 2026). "SKP2-mediated degradation of p27 has been regarded as an oncogenic driver and the SKP2-PTEN axis is implicated in breast cancer, lung cancer, prostate cancer, colorectal cancer, gastric cancer, and prostate cancer." (PMID 40002221, 2025). "In several tumors, such as breast cancer, osteosarcoma, and glioblastoma, overexpression of SKP2 was associated with poor prognosis." (PMID 37308972, 2023). "Previous studies have shown that the E3 ligase Skp2 plays a crucial role in tumorigenesis and Herceptin sensitivity in breast cancer by activating Akt signaling in an Akt K63-linked ubiquitination-dependent manner." (PMID 35301297, 2022). "Emerging evidences have reported that SKP2 is frequently overexpressed in prostate cancer, melanoma, nasopharyngeal carcinoma, and breast cancer, and associated with poor prognosis by enhancing tumor progression." (PMID 35831273, 2022). "Diosgenin significantly inhibited the cell viability and motility of breast cancer cells and stimulate apoptosis via suppression of S-phase kinase-associated protein Skp-2 in breast cancer cells." (PMID 35677108, 2022). "The F-box protein SKP2 is overexpressed in many cancers and is associated with an inferior prognostic outcome in gastric, colon and breast cancers." (PMID 34066546, 2021). "A SKP2 inhibitor inhibited proliferation of RB1-deficient breast cancer cells more efficiently than in RB1-proficient cells, and did so in a dose-dependent manner, consistent with previous observations." (PMID 33591981, 2021). "One group reported that EMT was correlated with high expression of SKP2 and that knockdown of SKP2 caused partial reversal of the EMT phenotype in paclitaxel-resistant breast cancer cells." (PMID 30999935, 2019). "In breast cancer, the levels of histone variant mH2A1 are low and the F-box protein Skp2 is responsible for mH2A1 degradation." (PMID 31248103, 2019). "Mutation detection of breast cancer patients in cBioPortal for Cancer Genomics showed SKP2 mutated at the F-box domain and PDCD4 mutated at the MA-3 domain, which is the eIF4A binding domain." (PMID 30760284, 2019). "The overexpression of CDK8 and Skp2, accompanied by low levels of mH2A1, is associated with an adverse prognosis in breast cancer patients." (PMID 31248103, 2019). "A previous study has also shown that low p27kip1 and high Skp2 are more frequently associated with poor prognosis among breast cancer patients." (PMID 29925812, 2018). "A recent study in breast cancer cell lines revealed the S-phase kinase-associated protein 2 (Skp2), which is a substrate recognition component of the SC ubiquitin ligase complex, targets ERα but not ERβ for degradation." (PMID 29643853, 2018). "In oral squamous cell carcinoma (OSCC) Tca8113 and breast cancer cell lines, rapamycin down-regulated expression of S-phase kinase associated protein-2 (SKP2) and increased FOXO3a protein stability." (PMID 27588026, 2016). "Our previous study has shown that acquisition of EMT is associated with overexpression of S-phase kinase-associated protein 2 (Skp2) in PR breast cancer cells." (PMID 25605244, 2015). "Conversely, fibroblast-secreted kynurenine promotes the formation of the E-cadherin/Aryl hydrocarbon receptor (AhR)/S-phase kinase-associated protein 2 (Skp2) complex, resulting in degradation of E-cadherin to increase breast cancer invasiveness." (PMID 25060643, 2014). "As a cell cycle modulator, Skp2 deficiency is reported to slow down the cell proliferation in breast cancer, prostate cancer cells." (PMID 25015320, 2014). "S-phage kinase-associated protein 2 (Skp2) and Myc coordinate to induced RhoA transcription and promote breast cancer metastasis." (PMID 23826080, 2013).
breast carcinoma (continued). "Cytoplasmic relocalization of Skp2 expression is associated with rapid proliferation, aggressive cellular behavior, and potentially with poor prognosis for breast carcinoma patients." (PMID 23300741, 2012). "Overexpression of SKP2 is associated with resistance to preoperative doxorubicin-based chemotherapy in primary breast cancer." (PMID 22309939, 2012). "We found that cytoplasmic Skp2 expression was significantly associated with DFS in breast carcinoma, confirming our Kaplan-Meier analysis." (PMID 23300741, 2012). "Cytoplasmic Skp2 expression is associated with aggressive prognostic factors, such as larger tumor size, and advanced histological grade of the breast cancers." (PMID 23300741, 2012). "Previous studies demonstrated that Skp2 was commonly overexpressed and associated with poor prognosis in a variety of human cancers, including gastrointestinal cancer, breast cancer, prostate cancer, lung cancer and nasopharyngeal cancer." (PMID 22533738, 2012). "A splice variant of Skp2, i.e. Skp2B with a variant C-terminal, has been reported to play different roles in breast cancers." (PMID 23300741, 2012). "Over-expression of the ubiquitin ligase Skp2 results in loss of the cell cycle inhibitor p27Kip1 and is associated with poor prognosis in early breast cancer." (PMID 18644126, 2008). "The association between Cks1, Skp2, and p27Kip1 and ER expression was also observed in breast carcinoma cell lines." (PMID 16168119, 2005). "It was discovered that the cytotoxic effects of curcumin to breast cancer cells may be influenced by the S-phase kinase-associated protein 2 (SKP2)-Cip/Kips pathway." (PMID 38505423, 2024). "However, inhibiting TLK2 leads to the downregulation of ERα, BCL2, and SKP2, causing cell cycle arrest in the G1/S phase and ultimately triggering apoptosis, which can help improve the prognosis of patients with breast cancer." (PMID 38343446, 2023). "Recent studies indicate that Skp2 deficiency renders Her2-positive breast cancer cells more sensitive to Herceptin treatment and prolongs the survival of Her2-positive patients, highlighting that Skp2 is an appealing therapeutic target to combine with Herceptin for cancer treatment." (PMID 37532777, 2023). "Treatment with apigenin and chrysin reduced liver cancer HepG2 and breast cancer MDA-MB-231 cell viability as well as induced apoptosis via down-regulation of S-phase kinase-associated protein-2 (Skp2) and low-density lipoprotein receptor-related protein 6 (LRP6) expression." (PMID 36144783, 2022). "For instance, repression of integrin expression by MYC in breast cancer cells has been linked to suppression of cell migration and metastasis, while another report suggests that Skp2 cooperates with MYC to induce RhoA transcription, thereby promoting metastasis." (PMID 36860495, 2022). "In addition, SKP2 stimulates breast cancer tumorigenesis through K48-linked ubiquitination of the tumor suppressor PDCD4." (PMID 35006464, 2021). "Furthermore, the expression level of SKP2 is negatively associated with the survival of cancer patients—including those with prostate cancer, breast cancer, or lung cancer —suggesting that SKP2 acts as an oncogene." (PMID 32429232, 2020). "Invasion and migration are important characteristics of an invasive cancer and genistein blocks invasion and migration of breast cancer cells by inhibiting S-phase kinase-associated protein 2 (Skp2), which is an important kinase frequently upregulated in multiple cancers." (PMID 31618928, 2019). "However, in a subset of breast carcinomas, it has shown that loss of p27 expression is an independent predictor of both overall survival and disease-free survival, as Skp2 is expressed at low levels despite low expression of p27." (PMID 30086790, 2018).
breast carcinoma (continued). "In a previous study, skp2 (S-phase kinase-associated protein 2) was significantly overexpressed in breast cancer samples and cell lines, and a high skp2 expression positively correlated with poor prognosis of breast cancer." (PMID 29743060, 2018). "In addition, it has been reported that overexpression of Skp2 is associated with resistance to doxorubicin-based chemotherapy in breast cancer, which further suggests its potential as a therapeutic target." (PMID 29925812, 2018). "Overexpression of Skp2 is associated with poor prognosis in breast cancer." (PMID 27582552, 2016). "As SIRT3 has been implicated to possess tumor suppressor function, this result suggests that loss of SIRT3 may lead to elevated Skp2 expression in breast cancers." (PMID 23230084, 2012). "However, in human breast carcinomas, the underlying mechanism and prognostic significance of cytoplasmic Skp2 is still undefined." (PMID 23300741, 2012). "Recent evidence suggests that Skp2 is encoded by an oncogene that may be overexpressed in a large variety of cancers, including breast cancer." (PMID 16859513, 2006). "Surprisingly, overexpression of Skp2 is associated with resistance and sensitization after pre-operative doxorubicin-based chemotherapeutically could aid in cancer cell death and successful chemotherapy in primary breast cancer patients." (PMID 38559562, 2024). "These insights establish a framework for developing computationally prioritized strategies to design targeted inhibitors aimed at disrupting oncogenic signaling and overcoming SKP2-driven drug resistance in breast cancer." (PMID 42292664, 2026). "In line with our findings, another recent study found that TEX19 promoted the progression of breast cancer by modulating SKP2-mediated ubiquitination of CDK4." (PMID 41233852, 2025). "In breast cancer cells, Skp2 overexpression has been shown to boost proliferation and inhibit apoptosis, affecting cell cycle phases." (PMID 39744562, 2025). "Genes involved in the enrichment of the PI3K-Akt-mTOR pathway included Runx2 and Skp2, which are involved in mammary gland development and breast cancer." (PMID 38059614, 2024). "Nonetheless, previous observations imply that FASN-mediated inhibition of the retinoblastoma (pRB) tumor suppressor pathway is the primary mechanism responsible for SKP2 induction in breast cancer cells." (PMID 39064589, 2024). "Collectively, our study reveals that FBXW2 functions as a tumor suppressor in breast cancer by restricting AKT-Moesin-SKP2 axis." (PMID 37736741, 2023). "In turn, SKP2 stabilizes Moesin by directing its non-degradable form of polyubiquitination and therefore AKT-Moesin-SKP2 oncogenic axis plays crucial role in breast cancer progression." (PMID 37736741, 2023). "The findings of Emi1 in breast cancer are similar to our findings, Emi1 mediates the anti-apoptotic and pro-proliferative carcinogenicity of Skp2 through PI3K/Akt signaling pathway." (PMID 37168048, 2023). "Taken together, these observations suggest that FBXW2 prevents breast cancer progression, at least partly, by negatively regulating SKP2 levels." (PMID 37736741, 2023). "We also identified an oncogenic AKT-Moesin-SKP2 axis which promotes breast cancer progression and FBXW2 restricts this axis to prevent cancer progression." (PMID 37736741, 2023). "Skp2 is overexpressed in many types of human cancers, such as breast cancer, non-small cell lung cancer (NSCLC), lymphoma, melanoma, pancreatic cancer, and prostate cancer." (PMID 36552825, 2022). "Liet al. reported that SCF SKP2 triggered K48-linked ubiquitination and degradation of PDCD4 in breast cancer." (PMID 35983977, 2022). "Skp2 is involved in the development of several tumor cells, such as lymphoma, prostate cancer, pancreatic cancer, breast cancer, nasopharyngeal cancer, and gastric cancer." (PMID 35845132, 2022).